C3 (complement C3)
Diseases named in the same sentence as C3 in open-access papers (continued):
Sharing a sentence is not in itself a finding about the gene and the disease.
COVID-19 (continued). "Interestingly, genetic variants of complement pathway genes, including C3, factor H, and complement decay-accelerating factor, were reported to be significantly associated with clinical outcomes in COVID-19." (PMID 34769508, 2021). "Decreased C3 levels in serum are associated with poor prognosis for COVID-19 patients." (PMID 34067609, 2021). "Additionally, our results suggested that decreased serum level of C3 is the immunity-related risk factor predicting mortality of patients with COVID-19." (PMID 32746940, 2020). "Additionally, we determined that neutrophilia, lymphocytopenia, low number of CD4+ T cells, and decreased level of C3 were the immunity-related risk factors that can predict mortality of patients with COVID-19." (PMID 32746940, 2020). "More importantly, targeting the complement system through inhibition of complement components, such as C3, C5, C5a and C5aR, has been suggested as a potential therapeutic strategy to reduce hyperinflammation, risk of thrombosis and other complications associated with severe COVID-19." (PMID 40725250, 2025). "Additionally, systemic inflammation caused by COVID-19, such as complement C3 decrease and IL-6, TNF-α increase, are risk factors for long-term lung symptoms and leads to diffuse parenchymal changes in the lungs, including alveolar damage, exudation, and pulmonary fibrosis." (PMID 39149538, 2024). "Since C3 and the lectin pathway have been implicated in the pathophysiology of coronaviruses infections, inhibitors of proximal complement pathways, under clinical development for complement-mediated TMAs, could also be efficacious in COVID-19." (PMID 32485958, 2020). "Multiple studies suggest that complement activation plays a key role in COVID-19 pathology, with C3 split products (e.g., C3a) often monitored by immunoassay." (PMID 39949890, 2025). "LN biopsies in COVID-19 are consistent with classic LN, which generally stains positive for deposits with IgG, C3, and C1q dominance." (PMID 40552181, 2025). "CD55 and CD59, but not CD46, are involved in the hyperactivation and deposition of the complement factors C3, C3b/iC3b/C3d and C5b-9 in infected lung lesions of coronavirus disease 2019 (COVID-19)-affected people." (PMID 39599800, 2024). "Other patients have been in similar situations, with COVID-19 and preexisting complement dysfunctions such as nonsense Factor H, CD46, and PIG-A mutations, and gain of function C3 mutations contributing to acute thrombotic microangiopathy (TMA)." (PMID 38368584, 2024). "Among the proteins involved in these enriched pathways, elevated C3 in COVID-19 patients with comorbidities was revealed." (PMID 38672194, 2024). "Among them, the cleavage of C3 (protein CO3) releases C3a anaphylatoxin, which contributes to the hyperinflammatory state of COVID-19 patients." (PMID 38672194, 2024). "Conditional C3 or C5 knockout mice are useful to dissect the role of local complement activation and production in the COVID-19 pathogenesis." (PMID 38368584, 2024). "By use of ingenuity pathway analysis (IPA) and publicly available ChIP-Seq of STAT1, interferon (INF)-JAK1/2-induced STAT1 signaling pathway is predicted to induce complement C3 expression and its activation in COVID-19 infected human lung epithelial cells." (PMID 38538870, 2024). "COVID-19 patients exhibit extensive deposition of complement components within the lung septal microvasculature, resulting in upgraded C3 in serum." (PMID 38173531, 2024). "We observed significant correlations between serum levels of complement components C3 and C4 among patients with COVID-19 and bacterial pneumonia." (PMID 38585537, 2023). "Two-colored western blot analysis (red for complement C3 and green for carbonyl) showed only fragments of complement C3 in the convalescent COVID-19 samples but both full-length complement C3 and fragments were observed in the healthy control plasma samples." (PMID 36765106, 2023).
COVID-19 (continued). "Children with acute COVID-19 had significantly elevated levels of C1q, C2, C4, C3, C5, C5a, C3b, factor B, factor H, and factor I in comparison with convalescent COVID-19 children." (PMID 36961465, 2023). "Our data indicates a partial activation of the complement system in hospitalized acute COVID-19 patients as indicated by the partial degradation of C3 main band in plasma samples of acuteCOVID-19 patients." (PMID 36765106, 2023). "Children with convalescent COVID-19 had significantly elevated levels of C1q, C2, C3, C3b/iC3b, C4b, C5, C5a, and MBL complement proteins and of complement regulatory proteins like factor B and factor H in comparison with children in the control group." (PMID 36961465, 2023). "Previous research on C3 inhibition via compstatin Cp40 showed the successful disruption of TF expression of neutrophils following COVID-19 serum-induced complement activation in vitro." (PMID 37239041, 2023). "SDS-PAGE and proteomic analysis also show fragmentation of the complement C3 protein specifically in convalescent COVID-19 plasma whereas only partial fragmentation was observed in acute COVID-19 patient plasma samples." (PMID 36765106, 2023). "We next asked if ION astrocytes in COVID-19 increase the expression of complement factor 3 (C3), which is a gene that is upregulated in and therefore a marker of putative neurotoxic “A1” astrocytes." (PMID 37483351, 2023). "The disappearance of the main C3 band and increased level of C3 fragments in convalescent COVID-19 plasma indicates the activation of an innate immune response of these patients that is sustained during recovery." (PMID 36765106, 2023). "Evidence evaluation indicated moderate quality evidence for COVID-19 incidence and serum complement components C3 and C4 in randomized controlled trials." (PMID 38044944, 2023). "All studies have been designed to address the safety and efficacy of the complement inhibition by targeting C1q/MBL, C3, or C5 in COVID-19-induced ALI/ARDS." (PMID 37006238, 2023). "COVID-19 can directly infect endothelial cells of the brain, potentially promoting clot formation and stroke; complement C3 seems to play a major role in this process." (PMID 37533859, 2023). "This study showed that the activity of C3 was stronger in bacterial pneumonia than in COVID-19, whereas the activity of C4 was stronger with COVID-19." (PMID 38585537, 2023). "The prevalence of abnormal C3 results over C4 in this study underscores the potential role of C3 as a pivotal factor in COVID-19 pathogenesis." (PMID 38585537, 2023). "Recently, a significant correlation has been found between the activation of complement component C3 and COVID-19 severity." (PMID 36793739, 2023). "The complement proteins C1q, C2, C4, C4b, MBL, C5, C5a, C3, C3b and complement factors such as factor B, factor D, factor H, and factor I were significantly enhanced in children with severe or moderate COVID-19 (eFigure 3, eTable 5, eTable 6 in Supplement 1)." (PMID 36961465, 2023). "Elevated levels of FB and an elevated C3b/C3 ratio are also observed in the plasma of COVID-19 patients requiring treatment in the intensive care unit and/or mechanical ventilation." (PMID 35204727, 2022). "COVID-19 patients with DM and cardiac injury presented a decreased number of immunocyte subsets, lower C3 concentration, and a higher level of interleukin-6 (IL-6) and immunoglobulin A (IgA)." (PMID 36123740, 2022). "The present study highlighted a decrease in the levels of complement C3 in COVID-19 survivors 6 months after discharge." (PMID 35288537, 2022). "Nonetheless, the C3 inhibitor AMY-101 was initially used in two case series to treat four COVID-19 patients with acute respiratory distress syndrome, all of whom eventually recovered." (PMID 36304162, 2022). "Some of these pathways, including allograft rejection, autoimmune diseases (IBD, SLE, T1D, AITD, RA), C3/C4/C5 complement system and COVID-19, overlapped across headache and thyroid traits." (PMID 36672757, 2022).
COVID-19 (continued). "The inhibition of C3 and C5 also increased platelet counts in patients with thrombocytopenia induced by COVID-19 and reduced the incidence of thrombosis." (PMID 35204727, 2022). "We similarly showed that pregnant participants with severe COVID-19 had upregulation of C3/C5 convertase, complement component C2, complement component C9, and complement C1q subcomponent subunit C, indicating increased complement activation." (PMID 36383608, 2022). "We found increases of the classical complement sentinel C1q and the downstream C3 component on circulating blood monocytes from COVID-19 patients when compared to healthy controls (HCs)." (PMID 35250994, 2022). "The complement system plays a role in the pulmonary inflammation phenotype occurring in SARS-CoV-2 patients, with several C3 and C5 inhibitors offering rapid clinical benefits for COVID-19 patients within three days." (PMID 36614003, 2022). "We aimed to investigate ability of serum complement C3, C4 to predict mortality in patients with critical COVID-19." (PMID 35729416, 2022). "We observed that a small but statistically significant increase of C1q and C3 complement deposition persisted in recovered COVID-19 patients over 6-weeks after infection suggesting residual complement activity." (PMID 35250994, 2022). "We found that COVID-19 patients had increased levels of monocyte membrane-bound C1q (mC1q) and C3 (mC3) when compared to healthy control individuals (HCs)." (PMID 35250994, 2022). "The findings agree with a recent study conducting a systematic review and meta-analysis, investigating possible differences in the serum concentrations of the complement components, C4 and C3, in COVID-19 patients with different severity and survival status." (PMID 34804055, 2021). "Currently, the efficacy of different monoclonal antibodies mostly specifically targeting C3 or C5a complement factors in COVID-19 is investigated in clinical trials (e.g., eculizumab or ravulizumab)." (PMID 34356880, 2021). "Expression of C3 was significantly higher in AT2 cells of patients with COVID-19 than those of uninfected donors, indicating that coronavirus infection of these cells induces C3 gene transcription in vivo." (PMID 33827897, 2021). "We searched PubMed, Web of Science and Scopus, between January 2020 and February 2021, for studies reporting serum complement C3 and C4, measures of COVID-19 severity, and survival." (PMID 34163491, 2021). "Investigation of the lung of deceased COVID-19 patient reported deposition of C3, C3a, as well as complement complex C5b-9 in the lung and elevation of C5a in the circulation." (PMID 33632295, 2021). "AMY-101, a cyclic peptide C3 blocker, is being used as an experimental drug in patients with COVID-19 with severe organ failure." (PMID 34066983, 2021). "The complement system contributes to endothelial injuries, and several preliminary studies suggested favorable effects of C3 or C5a inhibition in severely ill patients with COVID-19." (PMID 34769508, 2021). "Further, the interaction between FXIIIB and proteins in the complement system, such as C3 and C1q, deserves attention for COVID-19 as reasoned in the previous section." (PMID 33390179, 2021). "Given the clinical picture including COVID-19, depressed C3 complement level, acute kidney injury, normal ADAMTS13 level, and response to eculizumab, aHUS triggered by COVID-19 was the most likely diagnosis." (PMID 34903272, 2021). "Since the distribution of C1q deposition was similar than that of IgG, C4, and C3 in all cases, we concluded that the classical pathway is a common route of C activation in the lungs of our COVID-19 patients." (PMID 34440207, 2021). "According to the coordinated role of C3/C5 in inflammation and coagulation, which are critical features in COVID-19, C3/C5 have become worth exploring targets." (PMID 34321065, 2021).
COVID-19 (continued). "AMY-101, as a highly selective and potent C3 inhibitor, was first successfully used in Italy for the treatment with a COVID-19 patient with severe pneumonia and systemic hyper-inflammation." (PMID 33811541, 2021). "Both C3 cleavage products (C3b and C3d) were detected in the renal arteries and glomerular capillaries of the COVID-19 biopsies." (PMID 34065210, 2021). "In the late stages of COVID-19, inhibiting the abnormal activation of complement (C3 and C5) can widely control ARDS, and also control the systemic inflammation affecting the microvascular bed of the kidneys, brain and other important organs in severe cases." (PMID 34321065, 2021). "C3, the central hub of all complement pathways, represents a broad therapeutic target for potential anti-inflammatory therapy in COVID-19." (PMID 33811541, 2021). "COVID-19 patients had more often increased levels of IgG, IgE, and complement C4, but a decreased level of C3 in our study." (PMID 33061829, 2020). "The stable C3 fragment C3c was detectable in the glomeruli of 4/9 of the COVID-19 biopsies, while glomerular C3c signals were comparable in ATI and more frequent and stronger in HUS and DIC and lower in Ctrl." (PMID 33584662, 2020). "Severe COVID-19 patients exhibit widespread complement activation which is characterized by C3 activation, C3a generation, C3 fragment deposition and increased serum C5a levels." (PMID 33708109, 2020). "Expression of C3 was significantlyhigher in AT2 cells of patients with COVID-19 than those of healthy donors, indicating thatin vivo coronavirus infection induces C3 genetranscription." (PMID 32702726, 2020). "In the group of 12 severe COVID-19 patients, all patients had lower levels of C3, and eight of them (67%) also had lower levels of C4 than the normal reference range." (PMID 32713370, 2020). "In particular, the CS has gained attention as a potential therapeutic target in COVID-19 patients, and first experiences targeting C3 and C5 of the complement system have been published." (PMID 32922409, 2020). "In the material clogging plasma adsorbers used for extracorporeal therapy of patients with COVID-19 C3 was the dominant protein but collectin 11 and MASP-2 were also identified." (PMID 33584662, 2020). "An attempt to combat COVID-19 using the compstatin-based complement c3 inhibitor AMY-101 has been shown recently, resulting in a good clinical response." (PMID 32604797, 2020). "In this study, we found that both the content of C3 and C4 declined as the development of COVID-19, however, the decrease of C3 occurred earlier than C4." (PMID 32713370, 2020). "These early results demonstrate not only the role of complement in COVID-19, but the utility of C3 and C5 as therapeutic targets to improve patient outcomes." (PMID 33374356, 2020). "This case report preliminarily demonstrates the safe and effective use of AMY-101 in the treatment of severe COVID-19 and reinforces the need for further clinical studies of C3 inhibition as anti-inflammatory therapy." (PMID 33374356, 2020). "In the group of 38 moderate COVID-19 patients, 15 patients (39%) had normal levels of C3, and 34 patients (89%) had normal levels of C4." (PMID 32713370, 2020). "In addition, in the context of COVID-19 myocarditis patients from the GSE183850 dataset, B2M and C3 were established as diagnostic markers that were subsequently validated (AUC = 0.978 and AUC = 0.956, respectively)." (PMID 40230577, 2025). "Hypotheses from other contexts, such as COVID-19, propose that upstream C3 blockade may exert broader immunological effects than terminal C5 inhibition, potentially influencing viral susceptibility." (PMID 40860872, 2025). "Severe COVID-19 patients have high circulating C5a in their blood as well as high levels of processed C3, suggesting that uncontrolled complement activation might be involved in the severity of COVID-19." (PMID 38418557, 2024).
COVID-19 (continued). "Enhanced C3 cleavage and downstream release of C3a and C5a may contribute to the severe COVID-19 phenotype by promoting myeloid cell infiltration and propagating inflammation." (PMID 38368584, 2024). "Some evidence suggests that complement activity may contribute to COVID-19 severity in a dose-dependent manner, with higher concentrations of sC5b-9 (solubilized MAC), C5a, and C3 byproducts in particular being associated with respiratory failure." (PMID 38368584, 2024). "There were significant relationships in C3 and C4 levels between COVID-19 and pneumonia groups." (PMID 38585537, 2023). "Similarly, the ~ 42 kDa band of complement C3 was predominantly present in convalescent COVID-19 samples with only faint bands present in acute COVID-19 and healthy plasma samples." (PMID 36765106, 2023). "Lower C3 levels in TTP-like syndrome-diagnosed patients can indicate complement activation as one of the influential factors in initiating TTP-like syndrome in COVID-19 patients." (PMID 37350773, 2023). "Several studies have demonstrated the presence of complement system activation in patients with COVID-19, as evidenced by a decrease in both complement C3 and complement C4 levels, as well as a significant correlation between the decrease in disease severity and high mortality." (PMID 38092887, 2023). "In addition, clinical trials with complement inhibitors targeting either C5 or C3 in the treatment of severe COVID-19 cases are ongoing." (PMID 37051252, 2023). "Children with MIS-C, vs those with acute COVID-19, had significantly elevated GM levels of C3 (318.2 [70.7] ng/mL vs 237.7 [61.8] ng/mL), C5a (2614.0 [336.2] ng/mL vs 1826.0 [541.0] ng/mL), and MBL (79.0 [12.4] ng/mL vs 69.6 [14.7] ng/mL) (eFigure 1 and eTable 2 in Supplement 1)." (PMID 36961465, 2023). "Similarly, an investigation showed higher levels of C3a and C5a as well as C3-fragment deposition in the lung biopsy samples of severe COVID-19 patients." (PMID 36793739, 2023). "Children with acute COVID-19 also had significantly elevated levels of C1q, C2, C4, C3, C5, C3b/iC3b, C4b, C5a, and MBL complement proteins and of complement regulatory proteins like factor B, factor D, factor H, and factor I in comparison with control children (eTable 2 in Supplement 1)." (PMID 36961465, 2023). "However, a statistical correlation between complements C3, C5, and C5b-9 in COVID-19 patients with established clinical scores of SOFA and SAPSII has not yet been described." (PMID 37239041, 2023). "Furthermore, 67.1% of patients with COVID-19 and 33.3% of patients with bacterial pneumonia were admitted with normal levels of C3 and C4." (PMID 38585537, 2023). "Levels of C3a (an anaphylatoxin and cleavage product in the formation of the C3 convertase) were significantly raised, strongly confirming complement cascade activation in COVID-19." (PMID 37731491, 2023). "In the COVID-19-positive group, hemoglobin, hematocrit, white blood cells, lymphocytes, monocytes, basophils, C3 Complement, total cholesterol, LDL cholesterol, prothrombin time (PT), thyroid stimulating hormone (TSH), free T4 and estimated glomerular filtration rate (eGFR) eGFR were lower." (PMID 35632392, 2022). "Having shown that serum from patients with acute severe COVID-19 is compromised in its ability to opsonise K. pneumoniae with complement C3b and C4b, we tested whether the bactericidal activity of the serum was similarly affected." (PMID 35572551, 2022). "Upregulation of C1s (1.60-fold), C1q (1.53-fold), C2 (2.76-fold), C3 (1.9-fold), and C4b (2.45-fold) indicated that timely complement activation may contribute to COVID-19 in CMs." (PMID 35903092, 2022). "In the first, we measured a panel of complement biomarkers in 52 COVID-19 patients in the US and found elevated complement dysregulation markers C3a, C3a/C3, and sC5b-9/C3 ratios (i.e., reflecting complement over-activation and consumption) in those with severe COVID-19 at admission." (PMID 35572977, 2022).